BCL6 (BCL6 transcription repressor)
Diseases named in the same sentence as BCL6 in open-access papers (continued):
Sharing a sentence is not in itself a finding about the gene and the disease.
follicular lymphoma (73 papers, 2006 to 2026). Follicular lymphoma is a form of non-Hodgkin lymphoma characterized by a proliferation of B cells whose nodular structure of follicular architecture is preserved. "BCL6 is a transcriptional repressor important in germinal center formation, and dysregulation of BCL6 is associated with diffuse large cell lymphoma and follicular lymphoma." (PMID 40577202, 2025). "The analysis demonstrated that CD20-positive B cells co-expressed CD10 and BCL6, which are germinal center markers commonly associated with follicular lymphoma." (PMID 39840177, 2024). "This positive association of BCL6 with clinical outcome has also been observed in primary central nervous system lymphoma, follicular lymphoma, and DLBCL, possibly because BCL6 enhances chemotherapy responses." (PMID 37835497, 2023). "In a subset of BCL6 rearranged cases, IHC for BCL6 protein will show nuclear staining of the lymphocytes which can cause diagnostic confusion with follicular lymphoma." (PMID 21318155, 2011). "Fortunately, HSP110 is also a chaperone of BCL6, as shown in follicular lymphoma and Burkitt lymphoma, so HSP110 inhibition would prevent this bystander effect." (PMID 38773631, 2024). "Overall, the mutation profile of the MYC/BCL2/BCL6-TH group is very similar to that of the MYC/BCL2-DH group, characterised by frequent mutations in follicular lymphoma associated genes (BCL2, CREBBP, KMT2D, EZH2, TNFRSF14)." (PMID 38184753, 2024). "Pathological examination of the spleen from UtxΔ/ΔBrafV600E (BU-159) mouse revealed expansion of B220+BCL6+ GC B-lymphocytes, giving a picture resembling follicular lymphoma (FL)." (PMID 37198323, 2023). "In human follicular lymphoma, pharmacological inhibition of BCL6 liberates NOTCH2 expression, resulting in apoptosis." (PMID 35536646, 2022). "Resveratrol has been reported to increase CD69 expression by inhibiting expression of BCL-6 and subsequently induced apoptosis of transformed follicular lymphoma." (PMID 34633989, 2021). "Biopsy of the cervical node showed expanded lymphoid follicles with atypical germinal centers that were positive for CD10, BCL-2, and BCL-6, consistent with follicular lymphoma (FL)." (PMID 30271641, 2018). "The distinction between MALT lymphoma and follicular lymphoma can be problematic, particularly if the biopsy is small and the MALT lymphoma shows follicular colonization associated with up-regulation of CD10 and/or BCL6 in the intrafollicular compartment." (PMID 35053607, 2022). "The immunophenotype of the patient with follicular lymphoma is usually positive for CD10 and Bcl-6 (IHC)." (PMID 38335376, 2024). "The negativity for CD10, CD23, cyclin D1, and BCL6 can be helpful in the differential diagnosis of OAMZL versus small lymphocytic lymphoma (CD23+), mantle-cell lymphoma (cyclin D1+), and follicular lymphoma (CD10+BCL6+)." (PMID 35267569, 2022). "A distinction from follicular lymphoma (positive for CD10 and BCL6), mantle cell lymphoma (CD5, cyclin D1, and SOX11), and chronic lymphocytic leukemia (CD5, CD23, and LEF1) is needed." (PMID 35053607, 2022). "Among them, HGBL-DH was the most common, with 3 cases of MYC/Bcl-2 HGBL-DH (8.6%, including 2 cases complicated with follicular lymphoma) and 21 cases of MYC/Bcl-6 HGBL-DH (60.0%, including 1 case complicated with the hemophagocytic syndrome)." (PMID 35686130, 2022).
follicular lymphoma (continued). "The dysregulation of these oncogenes drives B-cell hematological malignancies such as follicular lymphoma (BCL2 translocation, MLL2 inactivation) DLBCL (e.g. BCL6, BCL2 and MYC translocation) or Burkitt’s lymphoma (MYC translocation)." (PMID 33912162, 2021). "In the follicular lymphoma (FL) microenvironment, CXCR5+ICOS+PD1+BCL6+ follicular helper T (Tfh) cells, which closely correlate with FL B cells in neoplastic follicles, play a major role in supporting FL." (PMID 34069564, 2021). "The well-studied BCL6 (B cell lymphoma-6, also known as ZBTB27) was initially identified as an oncogene frequently translocated/hypermutated in diffuse B cell lymphoma (DLBCL) and follicular lymphoma (FL) cells." (PMID 34349770, 2021). "It is distinguished from follicular lymphoma by negativity for CD10 and Bcl-6, from mantle cell lymphoma by negativity for CD5 and Cyclin D1, and from nodular sclerosing Hodgkin lymphoma by lack of CD30-positive lacunar cells (Reed–Sternberg cells)." (PMID 28353588, 2017). "Overexpression of BCL6 has been observed in 40% of DLBCL, 14% of follicular lymphomas, and 48% of nodular lymphocyte-predominant Hodgkin lymphomas." (PMID 24917186, 2014). "The pathology was follicular lymphoma grade 1: centrocyte or centroblast-like lymphoid cells in ill-defined geminal center-like structures were positive for CD20, negative for CD3, positive for CD10, BCL2, and BCL6." (PMID 40896064, 2025). "Although CD10 positivity in HCLc is rare, occurring in 5%–26% of the cases, it may lead to misdiagnosis as follicular lymphoma, known for coexpressing CD10, CD20, and BCL6." (PMID 40687069, 2025). "A negative representative for markers of germinal center lymphocyte, BCL-6, and CD10 may help differentiate from follicular lymphoma." (PMID 33585230, 2020). "Follicular center cell lymphoma is also a possibility which can be ruled out based on the bcl-6 and CD10 positivity." (PMID 25133005, 2014). "Absence of CD10 and bcl-6 staining are useful for excluding follicular lymphoma, and staining of cyclin D1 is helpful for excluding mantle cell lymphoma." (PMID 17284308, 2007). "Moreover, unrestricted expression of Kappa and Lambda chains ruled out plasmacytoma, while CD10 (−) and BCL-6 (−) findings suggested the exclusion of follicular lymphoma." (PMID 41179665, 2025). "Excisional biopsy of the right orbital mass showed follicular lymphoma grade 1: centrocyte or centroblast-like lymphoid cells in ill-defined geminal center-like structures were positive for CD20, negative for CD3, weakly positive for CD10, predominantly positive for BCL2 and BCL6." (PMID 40896064, 2025). "Furthermore, EMZLs are negative for CD10 and BCL-6, for which follicular lymphoma is usually positive." (PMID 23691402, 2013). "Moreover, CD5, CD23, CD10, CD21, BCL-6, and Cyclin D1 were all negative, which could exclude the diagnosis of small lymphocyte lymphoma, follicular lymphoma, and mantle cell lymphoma." (PMID 33585230, 2020). "Negative staining for cyclin D1/SOX11 and CD10/BCL6 is useful for distinguishing MALT lymphoma from mantle cell lymphoma and follicular lymphoma, respectively." (PMID 40831827, 2025). "The reactive germinal centers were positive for CD20, CD10, and BCL6 but negative for BCL2, further supporting a reactive process rather than follicular lymphoma." (PMID 40979025, 2025). "The neoplastic lymphocytes of follicular lymphoma characteristically express B-line markers (CD19, CD20, CD79a) and, in most cases, CD10, BCL6, LMO2, and BCL2; they are normally negative for CD5, CD23, and cyclin D1." (PMID 38534887, 2024). "Like follicular lymphoma, MCL is positive for CD20 and Bcl-2, but in contrast to follicular lymphoma, MCL is negative for CD10, BCL-6, as well as CD23." (PMID 27119356, 2016). "Additionally, some cases of follicular lymphoma can show marginal zone differentiation and are negative for CD10 and bcl-6." (PMID 37958219, 2023).
Burkitt lymphoma (66 papers, 2009 to 2026). A rare form of malignant mature B-cell non-Hodgkin lymphoma. "B-cell markers, including CD22, CD19, CD79a, CD20, Pax5, and germinal center markers, such as CD10 and BCL-6, are expressed in Burkitt lymphoma." (PMID 40115528, 2025). "For example, Burkitt lymphoma (BL) expresses markers that are characteristic of normal germinal centre B-cells (e.g., BCL6 and CD10)." (PMID 34625709, 2021). "BCL6 is a key regulator of normal germinal center B-cells and is expressed in Burkitt lymphoma and some DLBCL." (PMID 31712669, 2019). "Of note, a recent study described the first intron of BCL6 to be key in its overexpression in Burkitt lymphoma via altered DNA methylation." (PMID 30135684, 2018). "We screened a commercial natural product library consisting of 480 compounds for ability to prevent BCL6 induced transcriptional repression in the Burkitt's lymphoma cell line DG75." (PMID 24595451, 2014). "The immunophenotypic prototype of Burkitt’s lymphoma is IgM+/CD10+/bcl-2–/bcl-6+ with the Ki-67 proliferation index (PI) nearly at 100%; however, cases with an aberrant immunophenotype (such as bcl-2 expression) exist." (PMID 25364378, 2014). "Unlike sirtinol, cambinol can be used in vivo and was shown to effectively inhibit xenograft BCL6-expressing Burkitt lymphoma growth in mice." (PMID 22479397, 2012). "Indeed, repression was muted in BCL6-high Burkitt’s lymphoma cell lines (DAUDI and RAJI) with the characteristic chromosomal rearrangement of one or both alleles of the c-MYC promoter to the immunoglobulin heavy chain regulatory region." (PMID 40166243, 2025). "Similarly, STAT3 and CEBPB in SNB19 cell line, CHAF1A in IMR32 cell line, and BCL6 in Burkitt lymphoma cell line were identified by RegEnrich, with the GSEA method, as one of the top 20 key regulators in each corresponding dataset." (PMID 35017649, 2022). "Similarly, Bcl6 protein expression was down-regulated close to 50% in the presence of EBNA3C in Burkitt’s lymphoma cells and were dramatically suppressed in EBV-transformed LCLs." (PMID 28738086, 2017). "In addition, the expression of LITAF and BCL6 was assayed in six B-NHL cell lines including Burkitt's lymphoma cell lines (Raji, Daudi, Ramos and Namalwa) and DLBCL cell lines (OCI-Ly3 and OCI-Ly6) at mRNA and protein level." (PMID 27764808, 2016). "Interestingly, treatment of BCL6-expressing Burkitt lymphoma cells and Burkitt lymphoma xenograft mice with a dual SIRT1 and SIRT2 inhibitor, cambinol, produced a potent antitumor effect." (PMID 24259290, 2013). "Therefore, finding a positive relationship between the presence of Bcl-6 and Deptor may suggest that Deptor has some role in the development of Burkitt’s Lymphoma." (PMID 33412518, 2021). "Immunohistochemistry confirmed B-cell lineage (CD20, CD10, BCL6, c-MYC) with a Ki-67 index of 95%, consistent with Burkitt lymphoma." (PMID 42051830, 2026). "Burkitt lymphoma typically expresses CD10, CD19, CD20, and BCL6, with a Ki-67 proliferation index approaching 100%, reflecting its highly proliferative nature." (PMID 41180747, 2025).
Burkitt lymphoma (continued). "The immunohistochemistry results of laparoscopic biopsy revealed Burkitt lymphoma, characterized by positive expression of CD20, CD79a, CD10, BCL-6, MUM1, and strong positive expression of CD38, c-myc, cyclinD1, and Ki-67 positive index >90%+." (PMID 39993110, 2025). "We now demonstrate that BCL6 protein levels were dramatically decreased in Epstein-Barr virus (EBV)-positive lymphoblastoid cell lines and Burkitt’s lymphoma cell lines." (PMID 38864622, 2024). "A similar level of Bcl6 degradation, ranging from 59% to 84%, was detected in DLBCL and Burkitt’s lymphoma cell lines." (PMID 35954440, 2022). "In these cases, independently of the immunophenotype exhibited by tumor cells, MYC, BCL2, and BCL6 rearrangements should be investigated for the differential diagnosis among HGBL DH/TH, HGBL NOS, and Burkitt lymphoma." (PMID 31388760, 2019). "Overall BCL6 is an important oncogene in DLBCL but it is also expressed from an un-rearranged locus in follicular lymphoma, Burkitt's lymphoma and nodular lymphocyte predominant Hodgkin's lymphoma." (PMID 24595451, 2014). "Notably, CD10 and BCL6 serve as germinal center markers present in Burkitt lymphoma (BL) cases." (PMID 40428800, 2025). "Utilizing IHC staining for Bcl‐2, Bcl‐6, and TdT, LBL can be differentiated from Burkitt lymphoma." (PMID 36381035, 2022). "The role of BCL6 in Burkitt lymphoma has not been investigated but it is expressed in all cases and is likely to contribute to proliferation and survival." (PMID 31712669, 2019). "It has been reported that IRF4 inhibits cell cycle progression of GCB-derived Burkitt's lymphoma cells and induces terminal differentiation toward plasma cells through mechanisms independent of BCL6 downregulation." (PMID 27102442, 2016). "Burkitt lymphoma has a germinal center B-cell (GCB) immunophenotype and is positive for the pan-B-cell antigens CD20, CD79a, and PAX5, and germinal center antigens CD10 and Bcl6." (PMID 26416427, 2015). "Should the results for CD10 and BCL6 remain inconclusive, it may be advantageous to perform staining for BCL2, given that Burkitt lymphomas infrequently express this marker; however, it is noteworthy that certain DLBCL cases may exhibit variable expression of BCL2." (PMID 40428800, 2025). "The WHO-HAEM4 provisional entity “Burkitt-like lymphoma with 11q aberration” was named as such because of its clinical, morphological (“starry sky pattern”) and immunophenotypic (CD10+/BCL6+/BCL2−/Ki67 high) resemblance to Burkitt lymphoma but lack of MYC rearrangement." (PMID 36460764, 2023). "The definition of Burkitt lymphoma (BL) in WHO-HAEM5 remains largely unchanged, describing BL as an aggressive mature B-cell neoplasm composed of medium-sized cells with a germinal center B-cell phenotype CD10+, BCL6+, BCL2-/weak, high Ki67 index (>95%) and an IG::MYC juxtaposition." (PMID 35732829, 2022). "Immunohistochemistry staining in these tumors showed a typical immunoprofile of Burkitt’s lymphoma with positive staining for CD45, CD20, CD10, and BCL-6 and a negative result for BCL-2." (PMID 36634947, 2023). "It has a Burkitt-like immunophenotype (CD10+, BCL6+, BCL2−) but MYC expression is weak or negative, lacks MYC rearrangement, and is in contrast to Burkitt lymphoma 50% of the cases express LMO2." (PMID 37555980, 2023). "MYC rearrangements in DLBCL can be partnered with IGH but, compared with Burkitt lymphoma, are more frequently partnered with the IGL or to non-IG genes such as BCL6, BCL11A, PAX5 or ICAROS49." (PMID 26416427, 2015). "Positive staining for CD10, Bcl-6, and c-my, and the absence of HHV-8 are also helpful findings in Burkitt’s lymphoma." (PMID 24385757, 2013). "In contrast to Burkitt lymphoma (BL), where MYC is almost exclusively fused to an immunoglobulin locus, up to 50% of MYC translocations in DLBCL involve non-immunoglobulin genes, including among others BCL6, PAX5, and IKZF1." (PMID 35060000, 2022).
Burkitt lymphoma (continued). "Bcl‐6 is negative in LBL, while Bcl‐2 and TdT are negative in Burkitt lymphoma." (PMID 36381035, 2022). "As BCL2/BCL6 rearrangements by FISH were negative, Burkitt lymphoma (BL) was considered." (PMID 35845210, 2021). "Immunohistochemical and molecular studies demonstrated typical features of sporadic Burkitt lymphoma: the atypical cells were positive for CD20, CD79a, CD10, CD23, HLA-DR, bcl-6, PAX5, c-myc, and cytoplasmic IgM, but negative for CD3, CD5, CD15, CD30, CD34, TdT, bcl-2, and MUM1." (PMID 34868769, 2021).
leukemia (43 papers, 2005 to 2025). A malignant (clonal) hematologic disorder, involving hematopoietic stem cells and characterized by the presence of primitive or atypical myeloid or lymphoid cells in the bone marrow and the blood. "Here we identified a subset of high-risk leukemia characterized with high BCL6 and low BACH2 expression and associated with Ikaros dysfunction." (PMID 28030830, 2017). "Mutation causes dysregulation of proto-oncogene BCL6.Associated with leukemia and carcinoma." (PMID 31105874, 2019). "The aberrant expression of BCL6 can be provoked in leukemia cells in response to the tyrosine kinase inhibitor imatinib." (PMID 35503721, 2022). "Secondly, BCL6 was central to a receptor tyrosine kinase inhibitor (TKI) drug-resistance pathway, and BCL6 inhibition eradicated drug-resistant leukemia-initiating cells." (PMID 32320427, 2020). "The increased expression of BCL6 regulates the protection and maintenance of leukemia stem cells and the survival of pre B-cells." (PMID 32085659, 2020). "BCL6, which has been shown to be up-regulated in response to treatment with imatinib, represents a novel defense mechanism enabling leukemia cells to survive despite imatinib treatment." (PMID 30040819, 2018). "Bcl6-/- leukemia cells are poised to undergo cellular senescence and fail to initiate leukemia in serial transplant recipients." (PMID 24252550, 2013). "Indeed, pre-B-cell survival and the preservation and protection of leukemia stem cells are regulated by an enhanced expression of BCL6." (PMID 36834692, 2023). "Using in vivo functional approaches combined with molecular mechanistic analysis, we identified a reciprocal regulatory loop between B cell lymphoma 6 (Bcl6) and the RhoA-regulated transcriptional complex megakaryoblastic leukemia/serum response factor (MKL/SRF)." (PMID 37967194, 2023). "BCL6 has previously been demonstrated as a drug resistance mechanism through protective feedback signaling in response to the BCR-ABL1 targeting TKI imatinib in leukemia cells." (PMID 32234966, 2020). "In this cluster, the over-expression of PAX5 and TCL1A could also indicate presence of malignant immune cells as these genes are often found in leukemia and likely to contribute to oncogenesis BCL6." (PMID 32070336, 2020). "Studies suggest that pharmacological inhibition of BCL6 may be possible, representing a new strategy to eradicate leukemia initiation cells in CML." (PMID 31373443, 2019). "The acetylated BCL6 has critical functions in different leukemia." (PMID 30142192, 2018). "Moreover, targeting BCL6 high expression with BCL6-peptide inhibitor has an anti-proliferative effect in leukemia cells and the BCL6-peptide inhibitor strongly enhances the effect of PKI imatinib on apoptosis of CML cells." (PMID 28030830, 2017). "For example, the majority of BCR-ABL1+ leukaemias tend to display constitutive active cytokine signalling via activation of STAT5 and repression of BCL6." (PMID 41291054, 2025). "Thus, contrary to currently held views that stemness features critically underlie drug resistance in KMT2A-r leukemias, we found that upon targeting their cell cycle control vulnerability, the drug-tolerant cells corresponded to a more differentiated phenotype with expression of pre-BCR and BCL6." (PMID 38822412, 2024).